SOX2 (SRY-box transcription factor 2)
Diseases named in the same sentence as SOX2 in open-access papers (continued):
Sharing a sentence is not in itself a finding about the gene and the disease.
glioblastoma (continued). "Taken together, this accumulating functional and expression evidence positions SOX2 as an important and common signaling node for glioblastomas." (PMID 34732716, 2021). "SFRP2 was subsequently identified as a SOX2-antagonist, able to induce a mesenchymal glioblastoma subtype signature." (PMID 34021259, 2021). "The tumor-suppressive effect of Dazl was exerted through inhibiting the transcriptional activity of Oct4, Sox2, and Nanog gene to attenuate the stemness and resistance of glioblastoma cells." (PMID 32682409, 2020). "SOX2 mRNA was reported to contain m6A modification in embryonic stem cells and glioblastoma stem cells, and m6A modification of MYC mRNA was found in the CSCs of acute myeloid leukemia." (PMID 32676121, 2020). "By mediation of miR-137, downregulation of Nanog together with OCT-4 and SOX-2 expressions increased differentiation and decreased proliferation in glioblastoma stem cells." (PMID 32429463, 2020). "They showed that miR-429 applies a preventive influence on the propagation and invasion of glioblastoma cells by directly targeting SOX-2." (PMID 32429463, 2020). "The alliance of CD133Pos and SOX-2 is suitable for therapeutics targeting glioblastoma because of the critical role it plays in GSCs maintenance, causing resistance to chemotherapy and radiotherapy." (PMID 32429463, 2020). "SOX-2 has been evidenced to be abnormally expressed in a range of solid tumors, such as prostate cancer, lung cancer, breast cancer, glioblastomas, and melanomas." (PMID 32429463, 2020). "For instance, the overexpression of the SOX2 gene in the glioblastoma cell line has been observed despite the fact that the silencing of the SOX2 gene results in a decrease in the invasiveness and migration abilities of the cell line." (PMID 33152990, 2020). "In conclusion, Dazl functions as a novel cancer germline gene to initiate the stemness of glioblastoma cells by regulating the CD133/Oct4/Nanog/Sox2 regulatory axis and increasing the resistance of glioblastoma cells to Dox and TMZ." (PMID 32682409, 2020). "The expression of miR-148a can suppress the Oct-4/Sox-2-stimulated stem-cell like tumor cell proliferation in glioblastoma based on the suppression of stem cell markers." (PMID 32351328, 2020). "By upregulating miR-145 expression, cyclin-D1 and SOX2 are downregulated, leading to G0/G1 arrest in patient-derived glioblastoma spheres (PDGS) resulting in anchorage-independent growth inhibition." (PMID 32906592, 2020). "According to this, it was reported that mithramycin was able to reduce in vivo proliferation of glioblastoma cells through the downregulation of SOX2 expression and its target genes." (PMID 32295077, 2020). "It was shown to be overexpressed in glioblastoma, and studies suggest Sox2 as a prognostic factor for glioblastoma." (PMID 32260145, 2020). "In agreement with the enrichment of ALKBH5 expression in GSCs, the protein colocalized, in tumour tissues, with two typical stemness markers for glioblastoma, SOX2 and Nestin." (PMID 32316617, 2020). "The relationship between SOX2 and miR-486-5p is controversial and, although SOX2 expression is promoted by miR-486-5p in some tumors, such as glioblastoma, it inhibits SOX2 in liver cancer." (PMID 33227890, 2020). "SOX2 and OCT4 are overexpressed in a variety of cancers, including breast, prostate, lung and colorectal cancers, and glioblastoma and have been associated with CSC subpopulations in these tumors." (PMID 31500347, 2019). "SOX2 inhibition results in the downregulation of cyclin D1 and suppression of anchorage-independent growth and sphere formation of patient-derived glioblastoma." (PMID 30871066, 2019). "In cancer stem cells of osteosarcoma and glioblastoma, SOX2 antagonises upstream Hippo activators, leading to enhanced YAP function." (PMID 30912742, 2019).
glioblastoma (continued). "SOX2 is often highly expressed in glioblastoma and its knockdown reduces proliferation and tumourigenicity in glioblastoma tumour-initiating cells." (PMID 29759978, 2018). "Our previous study has shown that BP reduced SOX2 expression and stemness in glioblastoma cancer stem cells." (PMID 30287739, 2018). "A combination of the transcriptional regulators Sox2, Olig2 and Zeb1 is robustly expressed in genetically diverse glioblastomas and is sufficient to transform astrocytes that have lost tumour suppressor gene pathways." (PMID 29759978, 2018). "Compared to our previous studies, a consistent down regulation in SOX2 was also observed in glioblastoma stem cell." (PMID 30287739, 2018). "Their expression in differentiated cells strongly correlated with the down-regulation of transcription factors like OLIG2, POU3F2, SALL2, SOX2, capable of reprogramming differentiated glioblastoma cells into stem-like cells." (PMID 29773872, 2018). "The small molecule n-Butylidenephthalide (BP) reduced expression of AXL and stemness-related genes, including CD133, Sox2 and Oct4, in a dose-dependent manner in glioblastoma." (PMID 29642503, 2018). "One study found SOX2 to be amplified in 26% of serous ovarian cancers, and the SOX2 locus (3q26.33) was amplified in ~8% of glioblastoma cases, indicating that an increase in copy number is part of the puzzle regarding SOX2 expression in cancer." (PMID 28388544, 2017). "BIS depletion also inhibited GSC-like properties and SOX2 expression in glioblastoma cell lines under the same conditions." (PMID 28241425, 2017). "In line with this evidence, association analysis in the human glioblastoma cohort from the TCGA showed an inverse correlation between MKP1 and SOX2 (r = −0.207, p value = 1.3e−06) and also with SOX9 (r = −0.169, p value = 1.7e−04)." (PMID 29284798, 2017). "To address this question, we utilized an in vitro sphere culture system in which glioblastoma cells exhibited increased levels of SOX2, a representative stemness-related marker." (PMID 28642874, 2017). "Very recently, ZEB1 has been identified as a potential SOX2 target, which is co-expressed with SOX2 in glioblastoma." (PMID 29152086, 2017). "Penfluridol treatment suppressed the phosphorylation of Akt at Ser473 and reduced the expression of GLI1, OCT4, Nanog and Sox2 in several glioblastoma cell lines in a concentration-dependent manner." (PMID 28380428, 2017). "In tumors such as glioblastoma, ovarian, esophageal, lung, oral, prostate, and sinonasal carcinoma, SOX2 has been shown to be amplified in some subsets of patient tumors." (PMID 28388544, 2017). "For example, SOX2 is reported to be elevated in > 85% of glioblastoma multiforme samples compared to normal patient controls." (PMID 28388544, 2017). "Taken together, these data strongly suggested that SOX-2 is important for both tumorigenicity and drug resistance in glioblastoma stem cells." (PMID 28424427, 2017). "SOX2 has been reported to be deregulated in several human cancers including glioblastoma where is over expressed due to several mechanisms such as amplification and promoter hypomethylation." (PMID 27669421, 2016). "Our work provides a comprehensive view of the genome wide SOX2 regulated transcripts in GSCs, illustrating a complex scenario where SOX2 is the central player regulating different molecules and pathways in glioblastoma." (PMID 27669421, 2016). "Although SOX2 response program in a glioblastoma cell line has been analyzed, to the best of our knowledge, an exhaustive analysis of SOX2-regulated molecular circuitries in GSCs has not been performed." (PMID 27669421, 2016).
glioblastoma (continued). "Mer expression is also crucial for the maintaining primary glioblastoma-derived tumor spheres and increases expression of Nestin and Sox2 in a glioblastoma spheroid culture model." (PMID 27028863, 2016). "More solid and extensive preclinical results and clinical trials with the postulated combination of therapies in glioblastoma patients whose biopsies express elevated SOX2 are needed to establish their clinical impact." (PMID 27822457, 2016). "We present a comprehensive analysis of the transcriptome controlled by SOX2 in GSCs, gaining insights in the understanding of the potential roles of SOX2 in glioblastoma." (PMID 27669421, 2016). "SOX2 has been reported to play a pivotal role in developing drug resistance during glioblastoma treatment." (PMID 27791206, 2016). "In this study we present a comprehensive analysis of the transcriptome controlled by SOX2 in GSCs, gaining insights in the understanding of the potential roles of SOX2 in glioblastoma." (PMID 27669421, 2016). "In a previous work where the SOX2 response program in a glioblastoma cell line was analyzed, authors identified 489 genes whose expression were altered in response to SOX2 knockdown, using several genomic technologies." (PMID 27669421, 2016). "The downstream mechanisms that specifically drive SOX2-dependent invasion in glioblastoma remain to be identified." (PMID 27791206, 2016). "In this review, we will summarize the current knowledge about SOX2 in glioblastoma and recapitulate several strategies that have recently been described targeting SOX2 in this malignancy." (PMID 27822457, 2016). "In our series of 21 glioblastoma cases, foci of large ischemic necrosis were observed in 20 cases, among which the existence of SOX2+ HIF-1α+ RNApII-S2P-/low cells near large ischemic necroses was found in 16 cases." (PMID 26799577, 2016). "Understanding how factors such as SOX2 drive the glioblastoma tumor phenotype will aid in the development of new therapeutic approaches based on targeting GSCs." (PMID 27669421, 2016). "In support of this concept, another study demonstrated that Cdc20 drives invasiveness and self-renewal in patient tumor-derived GSCs (glioblastoma stem-like cells) through pluripotenty related transcription factor SOX2." (PMID 27626499, 2016). "We also analyzed the frequency and localization of tumor cells showing immunophenotypes other than SOX2+ HIF-1α+ RNApII-S2P-/low in the representative glioblastoma cases (n = 3)." (PMID 26799577, 2016). "The impact of SOX2 in glioblastoma cells has been further substantiated with overexpression studies." (PMID 27822457, 2016). "We compared the localization of SOX2+ HIF-1α+ RNApII-S2P-/low cells with that of HIF-2α+ cells in serial sections of glioblastoma tissues." (PMID 26799577, 2016). "It is interesting to note that among the down-regulated genes following SOX2 knockdown, F11R has been shown to be overexpressed in glioblastoma cells." (PMID 27669421, 2016). "Our study integrates for the first time the coding and non-coding transcriptome controlled by SOX2 in GSCs, gaining new insights about the molecular circuitries governing glioblastoma biology." (PMID 27669421, 2016). "We recently described a novel molecular circuit by which the core reprogramming transcription factors Oct4 and Sox2 regulate stem-like phenotypes and tumor propagating capacity in glioblastoma through DNMT-dependent regulation of microRNA networks." (PMID 27158195, 2015). "SOX2 has been previously silenced in glioblastoma cells derived from patient tumour samples, resulting in a reduction in cell proliferation and tumourigenicity both in vitro and in vivo." (PMID 26580604, 2015). "miR-142-3p is a target of Interleukin 6 (IL6) in glioblastoma and it has been proposed that miR-142-3p blocks the expression of IL6, Hmga2 and Sox2 thereby suppressing the stem like properties of glioblastomas." (PMID 26327117, 2015).
glioblastoma (continued). "It has been shown that murine and human embryonic stem cells and neural stem cells have high Sox2 activity, and increased Sox2 expression has also been found in breast and glioblastoma CSC populations." (PMID 24489842, 2014). "A comparison of tumor subtypes demonstrated that CD133+ glioblastoma cells had a lower incidence of cell apoptosis in the tumor tissue and higher protein expression levels of Oct4, Sox2, PCNA, EGFR, Ang2, MMP2 and MMP9 compared with CD133− cells." (PMID 23251243, 2013). "To address this question, we initially examined the impact of elevating SOX2 on the physiology of glioblastoma cells." (PMID 22937156, 2012). "While Gangemi and colleagues demonstrated that a reduction of SOX2 in glioblastoma tumor cells leads to a significant reduction in cell proliferation, it was unclear how glioblastoma tumor cells would respond to rapidly elevated levels of SOX2." (PMID 22937156, 2012). "Our findings with glioblastoma and medulloblastoma cells differ from those in other studies where it was reported that elevating SOX2 enhances the growth and tumorigenicity of DU145 prostate tumor cells, MCF7 breast tumor cells and A549 lung tumor cells." (PMID 22937156, 2012). "Here, we report that elevating SOX2 3-fold above endogenous levels in U87 and U118 glioblastoma, and DAOY medulloblastoma cells significantly impairs their ability to proliferate." (PMID 22937156, 2012). "In this study, we demonstrate that the levels of SOX2 must be maintained below a certain threshold in glioblastoma and medulloblastoma." (PMID 22937156, 2012). "In brain tumor initiating cells, hypomethylation of the SOX2 promoter has been directly correlated with SOX2 expression, and the SOX2 promoter is hypomethylated in aggressive glioblastoma patient samples." (PMID 22937156, 2012). "In this study, we demonstrate that elevation of SOX2 levels ∼2-fold in U87 and U118 glioblastoma cells leads to significant reductions in cellular proliferation by ∼65% and ∼55%, respectively." (PMID 22937156, 2012). "Quantitation of SOX2 levels in U118 glioblastoma cells demonstrated that SOX2 levels rose 2.1-fold one day after addition of Dox to the culture medium." (PMID 22937156, 2012). "In this regard, we demonstrate that a 2- to 3-fold increase in SOX2 levels in the population of glioblastoma and medulloblastoma cells decreases their proliferation and alters their cellular morphology." (PMID 22937156, 2012). "Together, our findings argue that the levels of SOX2 must be carefully controlled to support the growth of U87 and U118 glioblastoma cells, as well as DAOY medulloblastoma cells." (PMID 22937156, 2012). "In this regard, miR-145 has been shown to block the translation of SOX2 transcripts in glioblastoma cells." (PMID 22937156, 2012). "Taken together, these studies demonstrate that glioblastoma and medulloblastoma cells must carefully control the expression of SOX2 to support their proliferation." (PMID 22937156, 2012). "Glioblastoma-associated antigens such as AIM2, BMI1, COX-2, TRP2, GP100, EGFRv III, EZH2, LICAM, Livin/Livin β, MRP3, NESTIN, OLIG2, and SOX2 are present on these human GSCs." (PMID 22474481, 2012). "Together, these findings argue that SOX2 levels must be carefully controlled in glioblastomas and medulloblastomas to maintain their fate." (PMID 22937156, 2012). "The SOX2 gene promoter has been reported to be hypomethylated in clinical glioblastoma tumor samples, thereby enabling the expression of the SOX2 gene." (PMID 22937156, 2012). "In line with this, it has recently been reported that RNAi-mediated knockdown of SOX2 in glioblastoma tumor initiating cells (TICs) led to impaired proliferation." (PMID 22070920, 2011). "Variable percentage expression of Sox2 has been observed in gastric cancer, breast cancer, pancreatic cancer and glioblastoma, suggesting its relevance to cancer cell aberrant growth." (PMID 22184289, 2011).
glioblastoma (continued). "On the other hand, the same study revealed that the knockdown of SOX2 in glioblastoma TICs led to a moderate but sustained decrease in cell proliferation which was associated by a loss of Ki67 proliferation marker expression." (PMID 22070920, 2011). "Over expression of Sox2 and Twist1 in glioblastoma enhances tumor cell invasion and metastasis, thus supporting roles for Twist1 and Sox2 in glial tumorigenesis and progression." (PMID 22184289, 2011). "Interestingly, Sox2 is expressed by cancer stem cells (CSCs, Cancer Stem Cells, cancer cells with tumor-initiating properties) derived from pediatric brain cancers, and SOX2 knockdown arrests proliferation and results in a loss of tumorigenicity of glioblastoma CSCs." (PMID 20126410, 2010). "Interestingly, oscillatory expression of SOX2 has been observed in quiescent glioblastoma cells, reminiscent of HES1 oscillations in quiescent NSCs." (PMID 41142923, 2025). "In summary, this study demonstrated that All-Trans Retinoic Acid (ATRA) treatment significantly reduces the expression of the key stemness markers SOX2 and Nestin in the established glioblastoma cell lines U87-MG and A172, when cultured under neurosphere-promoting conditions." (PMID 40422249, 2025). "Studies have demonstrated that SOX2 is highly expressed in glioblastoma and is indispensable for key germinal stem cell (GSC) phenotypes including self-renewal and tumor initiation, demonstrating that proteasome regulation of SOX2 is critical for the maintenance and function of GSCs." (PMID 40034124, 2025). "The overexpression of SOX2 has been reported in several tumors, including glioblastoma." (PMID 39796258, 2025). "Also, we have previously demonstrated the colocalization of mHsp70 with markers of tumor stem-like cells (Nestin, SOX2) in glioblastoma cells." (PMID 41094345, 2025). "The Sox2–Hippo axis is conserved in other Sox2-dependent cancers such as glioblastomas." (PMID 38607003, 2024). "Interestingly, both CD44 and Sox2 are markers of radiation resistance in primary glioblastoma cultures, but CD44 expression correlates positively with radioresistance, while the Sox2-positive subpopulation shows the highest radiosensitivity." (PMID 38672482, 2024). "Additionally, the downregulation of SNHG6 in glioblastoma cells induces the expression of the stem cell marker SOX2 and modulates epithelial-mesenchymal transition through interactions with Notch1 and β-catenin." (PMID 39015773, 2024). "Furthermore, the SOX2 gene, a transcription factor responsible for inducing pluripotency in neural tissue and glioblastoma stem cells, was highlighted." (PMID 39347716, 2024). "Meanwhile, the immunohistochemistry results also supported that TSPAN6 could coexpress with stem cell marker Sox2 and division marker Ki67 (r = 0.86, p<0.0001) in glioblastoma tissues." (PMID 38725860, 2024). "By contrast, in spheroids derived from glioblastoma 14-60-4, the Cdkn2a and Mki67 mRNA levels were unchanged, and the transcription rates for Pik3cg, Pten, and Abcb1b increased dramatically, while Sox2 expression decreased, reaching minimal values recorded in the whole experiment." (PMID 38672482, 2024). "Additionally, the expression of another key gene, SOX2, which is important for glioblastoma stem cells, was also significantly upregulated." (PMID 39588508, 2024). "Thus, the SOX2-integrin αVβ5 appears to be crucial for the oncolytic activity of Zika virus against glioblastoma." (PMID 37896752, 2023). "SOX2 is a master transcription factor of mammalian cell pluripotency and stemness that also regulates the expression of several genes promoting self-renewal of glioblastoma stem cells (GSCs)." (PMID 37300955, 2023). "Sox2 promotes the proliferation, survival, and invasion of glioblastoma cells." (PMID 37833934, 2023).